MFN1 (mitofusin 1)
Diseases named in the same sentence as MFN1 in open-access papers (continued):
Sharing a sentence is not in itself a finding about the gene and the disease.
Obesity (23 papers, 2017 to 2026). Accumulation of substantial excess body fat. "The blockade of mitochondrial fusion via Mfn1 inhibition was closely associated with the process of insulin resistance and obesity." (PMID 36670935, 2022). "Mitofusins 1 and 2 (Mfn1/2) facilitate mitochondrial fusion in AgRP neurons, linking their function to obesity." (PMID 40130157, 2025). "We assessed the expression of Mfn1 and 2 in islets isolated from the leptin receptor deficient db/db BKS mouse model, which develops obesity, progressive β-cell mitochondrial and insulin secretory dysfunction, and eventual β-cell failure." (PMID 35487893, 2022). "Mutations of MFN1 and MFN2 are related to the development of neurological diseases, obesity, and vascular diseases." (PMID 36743936, 2022). "By contrast, inhibition of Mfn-1 and 2 in AgRP neurons in the hypothalamus prevented diet-induced obesity in rodents fed an HFD." (PMID 33227495, 2021). "Interestingly, although knocking down Mfn1 in the liver confers protection to mice against high-fat diet-stimulated insulin resistance and obesity, inhibiting the division-related proteins Fis1 and Drp1 in cells impairs cell respiration and insulin secretion." (PMID 40851002, 2025). "However, further studies are needed to clarify the different regulatory mechanisms of Mfn1, Mfn2, and Drp1 targeting mitochondrial metabolism in diabetes and obesity." (PMID 37942520, 2025). "Knockout of Mfn1 or Mfn2 genes disrupt ATP synthesis and breakdown, decrease intracellular ATP levels, reduce AgRP neuronal firing rate, and lead to reduced food intake and obesity." (PMID 40130157, 2025). "Additionally, obesity disorders can suppress MFN1-mediated mitochondrial fusion in the heart in rats, leading to increased cardiomyocyte apoptosis." (PMID 37711889, 2023). "Similarly, obesity was accompanied by higher protein levels of MFN1, thereby suggesting an augmented fusion that adapts the morphology of the mitochondria to the metabolic needs of the cell." (PMID 32079154, 2020). "However, further studies should determine the distinct regulatory mechanisms of Mfn1 and Mfn2 targeting mitochondrial metabolism in diabetes and obesity." (PMID 31551926, 2019). "This study also showed that, in the HFD-Con group, where obesity was induced, the expression of proteins related to mitochondrial fission, Drp1 and Fis1, increased, whereas the expression of proteins related to mitochondrial fusion, Mfn1, Mfn2, and Opa1, decreased." (PMID 31010272, 2019). "Results obtained in this work are supported by previous observations showing that the SKM of individuals with obesity and T2DM displays lower expression of Fis1 and DRP1 and higher Mfn1/2 expression relative to healthy subjects." (PMID 37627494, 2023). "In particular, several authors have argued that obesity is characterised by a reduced gene expression of OPA1 and MFN1 in rat liver and skeletal muscle, which may contribute to mitochondrial dysfunction." (PMID 35883794, 2022). "This increase in fusion (MFN1 and MFN2) and decrease in fission (FIS1) contribute to an increase in overall mitochondrial function, leading to a decrease in adiposity in HF fed mice, a consequent reduction in obesity, and a concurrent reduction in the development of NASH." (PMID 30057822, 2018). "As part of the mitochondrial fusion machinery, mitofusin 1 and 2 (MFN1 and MFN2, respectively) were significantly increased by DPR, irrespective of obesity, whereas optic atrophy 1 (OPA1) expression was unchanged." (PMID 41549510, 2026). "Mfn2, but not Mfn1, deletion in brown adipose tissue (BAT) remodels the mitochondrial dysfunction, leading to an increase in insulin sensitivity and resistance to obesity." (PMID 31551926, 2019). "While another study found Mfn1 and Mfn2 but not Opa1 were decreased, and Drp1 and Fis1 were increased in skeletal muscle of HFD-induced obesity mice." (PMID 29245950, 2017).
hepatocellular carcinoma (20 papers, 2018 to 2025). A malignant tumor that arises from hepatocytes. "Increased mitochondrial fission, due to elevated DRP1 to MFN1 ratio, causes higher ROS production, which supports cancer survival in hepatocellular carcinoma." (PMID 41146909, 2025). "The Drp1/Mfn1 expression ratio was found to be increased in hepatocellular carcinoma (HCC) tissues and was associated with a poor prognosis." (PMID 39123496, 2024). "Upregulation of the mitochondrial fission protein Drp1 has been linked to tumorigenesis in prostate cancer studies, whereas downregulation of fusion protein Mfn1 has been linked to tumorigenesis in hepatocellular carcinoma studies." (PMID 38092752, 2023). "Excessive mitochondrial fission and downregulated Mfn1 have been associated with hepatocellular carcinoma metastasis and a poor prognosis." (PMID 35933403, 2022). "The authors demonstrate that elevated FUNDC2 causes mitochondrial fragmentation through inhibition of MFN1 in hepatocellular carcinoma and that knockdown of FUNDC2 inhibits liver tumorigenesis in mice." (PMID 35710796, 2022). "Moreover, low levels of Mfn-2 expression correlate with a poorer prognosis in breast cancer patients and low Mfn-1 is associated with an increased metastatic capacity in hepatocellular carcinoma (HCC)." (PMID 35454774, 2022). "Loss of Mfn1 function triggers epithelial mesenchymal transition in hepatocellular carcinoma (HCC), which is supportive for HCC invasiveness and metastasis." (PMID 40438494, 2025). "For example, the mitochondria-associated dynamin and fission proteins DRP1 and MFN1, both of which are altered in expression in hepatocellular carcinoma, lead to an increase in mitochondrial fission thereby promoting the progression of hepatocellular carcinoma." (PMID 39012280, 2024). "The Drp1/Mfn1 expression ratio was found to be increased in hepatocellular carcinoma (HCC) tissues and associated with poor prognosis." (PMID 33498743, 2021). "Forced DRP1 overexpression or MFN1 knockdown can promote the viability and mitochondrial division of hepatocellular carcinoma cells 42-44." (PMID 41323781, 2025). "In hepatocellular carcinoma and cholangiocarcinoma, MFN1- and OPA1-mediated fusion is excessively activated, while the deletion of these genes impairs mitochondrial bioenergetics and inhibits cell growth." (PMID 41146909, 2025). "Increased mitochondrial fission by knockdown of MFN1 promotes the survival of hepatocellular carcinoma cells both in vitro and in vivo, mainly by facilitating autophagy and inhibiting mitochondria-dependent apoptosis." (PMID 36809297, 2023). "In contrast, overexpressing Mfn1, which restores mitochondrial fusion, slows the growth and spread of hepatocellular cancer." (PMID 37887021, 2023). "Lower MFN1 expression was found in hepatocellular carcinoma patients with more advanced disease and correlated with a worse overall and disease-free survival." (PMID 35356277, 2022). "Recent studies have shown that MFN1 regulates the metastasis of hepatocellular carcinoma through a metabolic shift from aerobic glycolysis to OXPHOS." (PMID 35413941, 2022). "In addition, excessive mitochondrial fission and the downregulation of mitofusin-1 (Mfn1) reportedly promotes metastases of hepatocellular carcinomas." (PMID 37887021, 2023). "Similarly, another group found increased DRP1 and decreased MFN1 mRNA expression in primary tumors from hepatocellular carcinoma patients in comparison to normal adjacent tissues." (PMID 35356277, 2022). "Moreover, a study found that overexpressing Mfn1 could restore mitochondrial fusion and inhibit hepatocellular carcinoma metastasis and proliferation." (PMID 35933403, 2022). "Increased mitochondrial fragmentation corresponded to an unfavorable prognosis for hepatocellular carcinoma (HCC) patients presumably due to concurrent Drp1 upregulation and downregulation of Mfn1." (PMID 29337889, 2018).
hepatocellular carcinoma (continued). "In hepatocellular carcinoma (HCC), MFN1 downregulation is related to metastasis and poor prognosis." (PMID 37627290, 2023). "To determine whether ASOs can be used to modulate mitochondrial dynamics, we administered a panel of ASOs targeting mitochondrial fusion and fission factors (Mfn1, Mfn2, Drp1, Fis1, Mff, Mief1, Mief2) to MHT (mouse hepatocellular carcinoma) cells in culture." (PMID 34698563, 2022).
cardiac hypertrophy (18 papers, 2018 to 2024). "Mfn1 and Mfn2 as regulators of mitochondrial size have been demonstrated in numerous studies, and hearts deficient in Mfn2 exhibit cardiac hypertrophy and have small fragmented IFM40." (PMID 35046471, 2022). "Mfn1/Mfn2 deficient mice and Tmem135 TG mice show cardiac hypertrophy while mice with induced processing of OPA1 develop dilated cardiomyopathy." (PMID 30102730, 2018). "Downregulation of Mfn1 has been observed in cardiac hypertrophy animal models, depicting its protective effect in cardiac hypertrophy." (PMID 37221368, 2023). "In contrast to cardiomyocytes with fusion defects due to Mfn1/Mfn2 knockout or fission defects due to Drp1 knockout, the Mfn1/Mfn2/Drp1 triple knockout cardiomyocytes exhibit prolonged survival and overt cardiac hypertrophy." (PMID 37895224, 2023). "Triple knockout of Drp1/Mfn1/Mfn2 remarkably delays the lethal effects of Drp1 deletion alone or Mfn1/Mfn1 deletion alone, exhibiting a concentric cardiac hypertrophy eventually leading to death between 3 and 6 months after tamoxifen treatment." (PMID 33712058, 2021). "MFN1 levels were negatively associated with those of 18-FDG uptake and positive with cardiac hypertrophy." (PMID 32079154, 2020). "Recent studies using a double KO of Mfn1 and Mfn2 and triple KO of Mfn1, Mfn2, and Drp1 mouse model demonstrated that the complete ablation of mitochondrial dynamics results in cardiac hypertrophy and HF due to diminished mitophagy." (PMID 30131726, 2018). "The systemic knockout of mitochondrial fusion proteins OPA1, MFN1, and MFN2 in mice are embryonically lethal, and the conditional combined deletion of MFN1/2 in adult cardiomyocytes triggers mitochondrial fragmentation, cardiac hypertrophy, and lethal dilated cardiomyopathy." (PMID 37175915, 2023). "Interestingly, mice with cardiac-specific Mfn1/Mfn2/Drp1 triple KO have a longer life and a unique pathological form of cardiac hypertrophy from that of Mfn1/Mfn2 double KO mice." (PMID 35665261, 2022). "Therefore, abnormal regulation of Mfn1 and Hspa9 might have detrimental effects on the normal function of the heart and potentially induce cardiac hypertrophy." (PMID 37221368, 2023). "Moreover, we found that only the re-expression Dnm1l and Mfn1 together could prevent the induction of cardiac hypertrophy by chronic mechanical overloading in a cell autonomous manner." (PMID 36276651, 2022). "Overexpression of Dnm1l and Mfn1 synergistically rescued YAP1-induced mitochondrial damages and cardiac hypertrophy." (PMID 36276651, 2022). "Recently, a study showed that compared to MFN1/MFN2 cardiac knockout or DRP1 cardiac knockout mice, MFN1/MFN2/DRP1 cardiac triple knockout mice survived longer and manifested a unique pathological form of cardiac hypertrophy." (PMID 35783853, 2022). "Additionally, studies have demonstrated that both miR-153-3p and miR-140 are involved in ISO-induced cardiac hypertrophy and ventricular hypertrophy in patients with pulmonary arterial hypertension (PAH), downregulating the expression of MFN1 mRNA and leading to excessive mitochondrial fission." (PMID 34122082, 2021). "However, the influence of Mfn1 on mitochondrial dynamics during cardiac hypertrophy is not yet fully understood." (PMID 31903137, 2020). "Strikingly, the simultaneous restoration of a mitochondrial fission activator DRP1 and a mitochondrial fusion activator MFN1 was necessary to rescue YAP-induced mitochondrial defects and cardiac hypertrophy, but overexpression of DRP1 or MFN1 alone did not." (PMID 36276651, 2022).
diabetes (17 papers, 2018 to 2025). "Under nutrient excess with glucose and high fatty acid, the levels of dynamic fusion proteins (Mfn1/Mfn2) were found to be lower in both diabetes-susceptible cybrid B4 and diabetes-resistant D4 cells." (PMID 32849261, 2020). "Moreover, Mfn1 deficiency leads to a highly fragmented mitochondrial network and enhanced mitochondrial respiration capacity in the myocardium and liver in diabetes." (PMID 31551926, 2019). "Levels of Fis-1 land Mfn-1 were significantly reduced in the Diabetes+Dapa group compared with the diabetes group (P < 0.05)." (PMID 36068525, 2022). "Specifically, MFN1 expression was approximately 50% lower in diabetes, diet, and combination exposed offspring hearts." (PMID 31242551, 2019). "Analyzing expression of both MFN1 bands together (70 kDa + 86 kDa) uncovered a trend towards lower MFN1 in both diabetes- and high-fat diet-exposed offspring." (PMID 31242551, 2019). "To examine the causal role of mitochondrial dynamics in insulin resistance relevant to mtDNA variants, we established cybrid cell harboring diabetes mellitus- (DM-) susceptible mtDNA haplogroup B4 (thereafter DM cybrid) and overexpressed Mfn1, Mfn2, Drp1, and Fis1 in cybrid B4." (PMID 30363990, 2018). "To address whether mtDYN plays a causal role in regulating cellular IR and serves as a potential therapeutic target, we have bidirectionally manipulated the expression of dynamic proteins, including MFN1, MFN2, DRP1, and FIS1 in cybrid cell harboring diabetes-susceptible haplogroup B4." (PMID 30363990, 2018). "This MFN1/2 regulation occurs through the control of TFAM expression, which is vital for mtDNA maintenance and glucose regulation in diabetes." (PMID 41465559, 2025). "In summary, OPA1, MFN1, MFN2 mRNA and protein expression analysis shows that mitochondrial fusion dysfunction occurs during the development of diabetes, resulting in abnormal mitochondrial morphology, and ShenQiWan can alleviate the renal injury by stabilizing the mitochondrial fusion process." (PMID 38026991, 2023). "Taken together, these results suggested that treatment with GCGR mAb could effectively attenuate the diabetes‐induced upregulation of CPT1B, OPA1, and MFN1, and oxidative stress in CMECs." (PMID 37596940, 2023). "Thus, the primary physiologic role of Mfn1 and 2 in β-cells is coupled to the preservation of mtDNA content rather than mitochondrial architecture, and Mfn1 and 2 may be promising targets to overcome mitochondrial dysfunction and restore glucose control in diabetes." (PMID 35487893, 2022). "As expression of MFN1 and MFN2 is reduced in cardiomyocytes and skeletal muscle of patients with diabetes, respectively, activators of Mfn1/2 may have additional benefits beyond improving β-cell function." (PMID 35487893, 2022).
myocardial infarction (15 papers, 2016 to 2025). Gross necrosis of the myocardium, as a result of interruption of the blood supply to the area, as in coronary thrombosis. "Irisin inhibits Mfn1 gene expression in heart tissue, and according to previous studies, deficient Mfn1 hearts are protected against acute myocardial infarction due to impaired mitochondria/SR tethering." (PMID 35890161, 2022). "Hearts deficient in both Mfn1 and Mfn2 protected against acute myocardial infarction, cardiomyopathy and sudden cardiac death." (PMID 28941171, 2017). "In summary, despite apparent mitochondrial dysfunction, hearts deficient in both Mfn1 and Mfn2 are protected against acute myocardial infarction due to impaired mitochondria/SR tethering." (PMID 27228353, 2016). "Metastasis-associated lung adenocarcinoma transcript 1 has been shown to inhibit mitochondrial dynamics and apoptosis through the miR-26b-5p/MFN1 pathway to improve cardiac microcirculation after myocardial infarction." (PMID 38694924, 2024). "It was shown that acute ablation of both cardiac Mfn1 and Mfn2 makes the heart resistant to acute myocardial infarction." (PMID 35890161, 2022). "In contrast, mice cardiomyocytes with Mfn1 knockout are protected from oxidative stress, and double knockout of Mfn1 and Mfn2 preserves mice hearts from acute myocardial infarction." (PMID 35912118, 2022). "Acute knockout of Mfn1 and Mfn2 in the heart showed a short-term protective effect against acute myocardial infarction, related to the decreased contact between mitochondria and endoplasmic reticulum, thereby reducing the calcium overload in the mitochondria." (PMID 34660720, 2021). "We found that the acute ablation of both cardiac Mfn1 and Mfn2 protected the heart against acute myocardial infarction." (PMID 27228353, 2016). "In summary, we have shown that acute ablation of both cardiac Mfn1 and Mfn2 rendered the heart resistant to acute myocardial infarction." (PMID 27228353, 2016). "Previous studies have highlighted the role of disordered expression of lncRNA-H19 in the development of cardiovascular diseases and demonstrated that lncRNA MALAT1 regulates mitochondrial dynamics post-myocardial infarction while inhibiting myocardial apoptosis through the miR-26B-5p/Mfn1 axis." (PMID 40162308, 2025). "This adds value to our result, as irisin might also protect the heart against myocardial infarction by inhibition of Mfn1 gene expression." (PMID 35890161, 2022). "In a study conducted on mice, the researchers found that the absence of MFN1/2 in hearts prevented acute myocardial infarction." (PMID 38694924, 2024). "Interestingly, another study reported the opposite observation, they showed that ablation of MFN1 and MFN2 genes had a protective effect on myocardial infarction, and the mechanism was related to inhibition of MPTP opening, reduction of oxidative stress, and attenuating mitochondrial Ca2+ overload." (PMID 35783853, 2022). "Additionally, MFN1 levels have been found to decrease in myocardial hypertrophy, while MFN2 levels increase under oxidative stress, however, MFN2 levels in the late stage after myocardial infarction and diabetis late stageare significantly reduced." (PMID 34660720, 2021). "In addition, exercise increases the activities of MFN1 and MFN2GTPase in myocardium, reverses the translocation of DRP1 to mitochondria, promotes mitochondrial dynamic remodeling, and effectively alleviates mitochondrial dysfunction in rats with myocardial infarction." (PMID 40076760, 2025).